KDM5C (lysine demethylase 5C)
Diseases named in the same sentence as KDM5C in open-access papers (continued):
Sharing a sentence is not in itself a finding about the gene and the disease.
cancer (continued). "Co-occurring of genetic mutations in cancers with KDM5C alterations were not uncommon in both early-stage and advanced stage cohort and some of them are prevalent driver genes (e.g., LRP2, KMT2C, PBRM1, NOTCH1, FAT1, SETD2, NSD1, etc.), while their clinical significance remained undetermined." (PMID 33953726, 2021). "The histone demethylases JARID1B and KDM5C, members of the JMJC family, are capable of demethylating H3K4 and are overexpressed in HCC and other types of cancer." (PMID 40699663, 2025). "Lysine demethylases 5C (KDM5C) and KDM6A were identified as cancer driver genes that support histone demethylation and hypoxia reprogramming in cancer metabolism 40-42." (PMID 39991574, 2025). "The results of the MS analysis indicated that a number of proteins potentially interact with KDM5C, including YY1, the overexpression of which has been observed in the vast majority of cancers." (PMID 39433896, 2024). "Analysing the top 100 co‐expressed genes of UBA1 in pan‐cancer on GEPIA2.0, the top 5 genes (CDK16, ELK1, KDM5C, RBM10 and TBC1D25) were highly correlated with UBA1 in most cancer types." (PMID 39183260, 2024). "Taken together, our study revealed a synergistic regulatory effect of KDM5C and YY1 on cancer cell proliferation and cell cycle progression." (PMID 39433896, 2024). "Lysine demethylase 5C (KDM5C), KDM6A, and ATRX chromatin remodeler (ATRX) are X-escapees that directly regulate epigenetics and play substantial roles in cancer protection." (PMID 38949020, 2024). "Taken together, our results indicate HIF1A-KDM5C as a new, relevant cancer axis in GBM, opening a new, interesting field of investigation based on KDM5C as a potential therapeutic target of the hypoxic microenvironment in GBM." (PMID 36142158, 2022). "Moreover, analysis of TCGA pan-cancer transcriptional and mutational data revealed that the association of KMT2C/BCOR/KDM5C mutations with DNA repair pathway score did not well correlate with the association of KMT2C/BCOR/KDM5C mutations with TMB in the same cancer type." (PMID 35681795, 2022). "Nonetheless, further studies are required to confirm the specificity of Rh(III) complex 1 on KDM5A over KDM5B, KDM5C, KDM5D, or other lysine demethylases in other cancers to fully assess their potential in cancer treatment." (PMID 36509829, 2022). "TRIM11 expression was correlated with progressive cancer stage, higher in all IIA, IIB, IIIA and IIIB stages, while KDM5C behaved the opposite." (PMID 36192394, 2022). "The adjacent genes to the enhancers regulated by KDM5C and TRIM11 were enriched in pathway in cancer, immune response, fatty acid metabolism and wound healing." (PMID 36192394, 2022). "KDM5C re-expression suppressed the glucose flux through PPP and re-sensitized cancer cells to ferroptosis." (PMID 34522206, 2021). "In the ICI treatment cohort, we firstly identified 1661 patients with different cancers receiving ICI therapy and 73 of them with KDM5C alterations." (PMID 33953726, 2021). "In myeloid malignancies KDM5A and KDM5B show enzymatic activity towards H3K4me3 while little is known about KDM5C and KDM5D in this context." (PMID 34944554, 2021). "Whole-exome sequencing analyses of ccRCC revealed that in addition to VHL, JARID1C/KDM5C, UTX/KDM6A, and SETD2 (H3K36 methyltransferase) were new cancer genes in ccRCC61." (PMID 31221981, 2019). "Among the several isoforms of histone demethylases, JARID1C/KDM5C and UTX/KDM6A have been identified as cancer drivers." (PMID 31221981, 2019). "Inactivating mutations in PBRM1, SETD2, KDM5C and BAP1 tend to be focal in the tumors, so therapies that are designed to exploit the weakness induced by mutation of an individual gene could be problematic since it cannot treat the remaining cancer cells free of that mutation." (PMID 30355451, 2018). "The other five genes: RECQL4, MYCL1, KDM5C, NUMA1, and PCM1 are documented in the cancer Gene Census list." (PMID 26998479, 2015).
cancer (continued). "It is worth noting that five of these genes (PIK3CA, HRAS, AKT1, ETV6, and KDM5C) are known to play important roles in cancer and are CGC genes (that is, experimentally validated cancer genes)." (PMID 25360158, 2014). "Specifically, silencing KDM5C and JARID1B leads to the epigenetic silencing of bone morphogenetic protein 7 and phosphatase and tensin homolog (PTEN), thereby reducing the migration, invasion, and wound-healing abilities of cancer cells." (PMID 40699663, 2025). "KDM5C and JARID1B are histone demethylases in the JmjC domain-containing protein family, primarily responsible for H3K4 demethylation to suppress gene expression through heterochromatin formation, and they are overexpressed in various cancers." (PMID 40699663, 2025). "In 15 cases (3 FTCs, 10 PTCs, and 2 PDTCs), there was no detectible KDM5C staining in the examined cancer samples." (PMID 38610938, 2024). "Among the constitutive escapees, there are the highly biomedically-relevant genes DDX3X, KDM5C and KDM6A, whose escape may contribute to lower cancer incidence in females than males." (PMID 36802379, 2023). "However, each KDM5 member has individual cancer implications and different binding patterns have been reported for KDM5B and KDM5C." (PMID 36631623, 2023). "KDM5C alterations have been proposed as a negative prognostic marker in various cancers and have been also used to predict survival benefits upon immune checkpoint inhibitor treatments." (PMID 36142158, 2022). "Additionally, sufficient studies have suggested that SETD2, BAP1, mTOR, MUC16, HMCN1, KDM5C, ARID1A, and PTEN are intimately tied to prognosis and immune response in cancers." (PMID 35936012, 2022). "For cancer subgroups, TRIM11 and KDM5C were significant correlated in Her2 subgroup." (PMID 36192394, 2022). "These suggest TRIM11 regulates immune gene expression through targeting KDM5C, which may serve as a new mechanism for TRIM11’s function in cancer immune response." (PMID 36192394, 2022). "Notably, we detected aberrant expression of XIST, the essential X-chromosome-inactivation lncRNA that is not normally expressed in males, and upregulation of genes known to escape X-inactivation, including male-biased cancer-related genes KDM6A, DDX3X, KDM5C, and ZRSR2." (PMID 42070154, 2026). "KDM5C alterations were a negative prognostic marker in whole group but it might be utilized to predict survival benefit from ICI treatment across diverse cancers." (PMID 33953726, 2021). "Interestingly, our panel included genes already described to be cancer predisposition genes (FAS, ITK, KIF1B, PGR and MET) or previously reported as playing important roles in cancer (ABI1, ARID5B, DNMT3A, HEY1, KDM5C, NCOA1, NUP98, and SLC34A2), or in DNA repair process (FANCF)." (PMID 30925779, 2019). "Since our hypothesis is that BAP1, PBRM1, KDM5C, SETD2 are critical to maintain the expression and/or function of ISGF3 subunits in the ccRCC cancer cells, we concluded that mRNA levels in the bulk tumors from the TCGA dataset are not suitable for our validation experiments." (PMID 30355451, 2018).
neurodevelopmental disorder (7 papers, 2020 to 2024). A behavioral and cognitive disorder with onset during the developmental period that involves impaired or aberrant development of intellectual, motor, or social functions. "Claes–Jensen type (OMIM#300534), an X-linked syndromic neurodevelopmental disorder, is caused by mutations in the KDM5C gene (OMIM*314690)." (PMID 36553533, 2022). "It is worth noting that genes encoding other members of the KDM5 family, KDM5B and KDM5C, are disrupted in neurodevelopmental disorders." (PMID 33350388, 2020). "This case report provides evidence for an emerging and phenotypic variability that adds to the literature of the role of KDM5C in females with neurodevelopmental disorders as well as movement disorders." (PMID 34530748, 2021). "The fact that mutations in KDM5A, KDM5B, and KDM5C all cause neurodevelopmental disorders, indicates that their function in the brain is nonredundant." (PMID 33350388, 2020).
neurodegenerative disease (1 paper, 2020). A disorder of the central nervous system characterized by gradual and progressive loss of neural tissue and neurologic function. "In some studies, silencing histone demethylases, such as KDM5C, the most abundant form of KDM5 in the brain, is associated with beneficial effect in neurodegenerative diseases such as Huntington’s disease." (PMID 33116116, 2020).
KDM5C also shares sentences with these, for which no sentence is quoted: bladder cancer (3 papers); neurological disorders (3); ovarian carcinoma (3); Alpha-thalassemia (2); blood cancers (2); developmental delay (2); diabetes (2); Huntington disease (2); Intellectual Disability Syndrome (2); von Hippel-Lindau disease (2); Angelman syndrome (1); ascending aortic aneurysm (1); brain cancer (1); cardiofaciocutaneous syndrome (1); chronic pancreatitis (1); coloboma (1); Cowden syndrome (1); depression (1); EARS disease (1); gastric tumors (1); glycine encephalopathy (1); hypogonadism (1); infection (1); Kabuki syndrome 1 (1); medulloblastoma (1); microphthalmia (1); movement disorder (1); Mowat-Wilson syndrome (1); non-small cell lung carcinoma (1); osteosarcoma (1).
A further 13 diseases each share a sentence with KDM5C in 1 paper.